KCNQ1OT1 (KCNQ1 opposite strand/antisense transcript 1)
Diseases named in the same sentence as KCNQ1OT1 in open-access papers (continued):
Sharing a sentence is not in itself a finding about the gene and the disease.
tumor (87 papers, 2006 to 2025). "Upregulation of KCNQ1OT1 expression in ESCC tissues was associated with larger tumor size and advanced TNM stage." (PMID 33909822, 2021). "It has been reported that lncRNA KCNQ1 overlapping transcript 1 (KCNQ1OT1) is abnormally expressed in multiple cancers and closely linked to tumor progression." (PMID 34704918, 2021). "Tumor volume and weight were reduced caused by KCNQ1OT1 downregulation, verifying that KCNQ1OT1 deficiency hindered tumor growth in vivo." (PMID 32760218, 2020). "Importantly, literature has verified that KCNQ1OT1 is highly expressed in CC patient cancerous tissues and CC cell lines and tightly associated with tumor volume increase, poor differentiation and radioresistance." (PMID 34704918, 2021). "Apart from that, our data verified that KCNQ1OT1 deficiency could suppress CRC tumor growth partly through the miR-329-3p/CTNND1 pathway in vivo." (PMID 32760218, 2020). "The loss of KCNQ1OT1 expression may have a certain inhibitory effect against tumor response." (PMID 35432529, 2022). "These regulatory molecules have demonstrated significant roles in cancer progression: NEAT1 functions as an oncogenic lncRNA in multiple malignancies, while KCNQ1OT1 serves as a tumor promoter through various mechanisms." (PMID 41378121, 2025). "Further analysis revealed changes in genes involved in DNA replication and cell cycle, providing evidence that KCNQ1OT1 is involved in tumor progression." (PMID 39123348, 2024). "Our study comprehensively analyzed the DEGs through bioinformatics and found scarce oncogenicity through tumor xenograft silencing KCNQ1OT1 in HCT116 cells." (PMID 38361755, 2024). "In this regard, the potential mechanistic involvement of lncRNA KCNQ1OT1 in tumor immune escape has been explored." (PMID 36591473, 2022). "ISH was performed in 86 pairs of LSCC and non‐tumour tissues to verify the level of KCNQ1OT1 was significantly increased in LSCC." (PMID 34850551, 2022). "Specifically, tumor-derived EVs carrying c-Myc blocked miR-556-3p expression by upregulating KCNQ1OT1 to elevate CLIC1 expression, thus activating the PI3K/AKT pathway and accelerating GC cell proliferation, invasion, and migration." (PMID 35260554, 2022). "Real-time PCR analysis showed that the expression of lncRNA KCNQ1OT1 in tumor tissues of nude mice was decreased significantly after lncRNA KCNQ1OT1 knockout." (PMID 35432529, 2022). "Tumor-derived EVs, EVs-c-Myc, KCNQ1OT1 or CLIC1 overexpression, or miR-556-3p inhibition promoted GC cell proliferative, invasive, and migrative capacities but repressed their apoptosis through activating PI3K/AKT pathway." (PMID 35260554, 2022). "The results of MeRIP‐qPCR showed that KCNQ1OT1 was significantly low m6A methylation in LSCC compared with that in non‐tumour tissues." (PMID 34850551, 2022). "The results showed that the expression level of KCNQ1OT1 in invasive tumor tissues was significantly higher than that in noninvasive tissues." (PMID 35432529, 2022). "Collectively, tumor-derived EVs carrying c-Myc activated KCNQ1OT1 to downregulate miR-556-3p, thus elevating CLIC1 expression to activate the PI3K/AKT pathway, which facilitated the growth and metastasis of GC." (PMID 35260554, 2022). "Compared with the sh-NC group, the downregulation of lncRNA KCNQ1OT1 significantly inhibited the tumor growth of HP75 cells in nude mice." (PMID 35432529, 2022). "Tumor weight detection results showed that when KCNQ1OT1 was knocked down, tumor weight was significantly reduced." (PMID 35432529, 2022). "In this study, inhibition of KCNQ1OT1 was found to inhibit tumor angiogenesis at the cellular level and animal tumor tissue level." (PMID 35432529, 2022). "The expression of lncRNA KCNQ1OT1 was found to be markedly increased simultaneously in both, exosomes generated from tumor cells and tumor tissues." (PMID 36338993, 2022).
tumor (continued). "Further, we found that lncRNA KCNQ1OT1 participated in dysregulation hallmarks such as self-sufficient growth signals, insensitivity to antigrowth signals, sustained angiogenesis and tumor-promoting inflammation." (PMID 33994860, 2021). "Among all tumor samples and paired normal tissues, KCNQ1OT1 was exclusively highly expressed in AML." (PMID 34404765, 2021). "In order to crystallize the biological function of KCNQ1OT1 in CC, RT-qPCR was applied for evaluating the expression differences of KCNQ1OT1 in CC tumor tissue specimens and adjacent non-tumor tissues." (PMID 34704918, 2021). "HYOU1 overexpression counteracted the inhibition of KCNQ1OT1 knockdown on the malignant behaviors of CC and tumor growth." (PMID 34704918, 2021). "We screened eight pairs of patients with different lncRNAs in tumor tissues and adjacent tissues by GEO analysis and found that KCNQ1OT1 was significantly higher in tumor tissues than that in adjacent tissues." (PMID 34350172, 2021). "The clinicopathological characteristics, including overall survival, lymphatic meta-stasis, TNM stage, and tumor size, are also positively correlated with lncRNA KCNQ1OT1 expression levels in cancers 16-19." (PMID 33994860, 2021). "In these GEO datasets, KCNQ1OT1 ceRNA network signature GSVA scores were significantly higher for tumor samples than for normal samples, which indicated the disease specificity of this KCNQ1OT1 ceRNA network." (PMID 34630508, 2021). "The silencing of KCNQ1OT1 inhibited GC tumor growth, reduced cell proliferation, and induced GC cell apoptosis by binding to miR-145-5p, modulating the expression of ADP-Ribosylation Factor 6 (ARF6)." (PMID 34827600, 2021). "Here, we first identified that KCNQ1OT1 was exclusively highly expressed in AML among all tumor samples and paired normal tissues, whereas within AML, expression of KCNQ1OT1 was higher in APL than other subtypes of AML." (PMID 34404765, 2021). "The data indicated that down-regulation of KCNQ1OT1 remarkably suppressed tumor volumes and weight compared with the control groups." (PMID 33345272, 2021). "We found correlations between lncRNA KCNQ1OT1 expression levels and tumor prognosis and immune cell infiltration." (PMID 33994860, 2021). "The mechanism by which lncRNA KCNQ1OT1 affects tumors through the regulation of the immune microenvironment is still unclear, so we investigated the role of lncRNA KCNQ1OT1 in tumor immune infiltration in this research." (PMID 33994860, 2021). "Emerging researches suggested that KCNQ1OT1 was involved in the occurrence, metastasis, and drug resistance of tumor via acting as a sponge for miRNAs, such as miR-217, miR-212-3, and miR-504." (PMID 33345272, 2021). "Obviously, up-regulated KCNQ1OT1 expression was observed in tumor tissues in comparison with paracancerous tissues." (PMID 34704918, 2021). "Although through these results we have verified that KCNQ1OT1 can promote tumor development through the autocrine effect of exosomes, its action form and pathway still bother us." (PMID 34350172, 2021). "Loss of KCNQ1OT1 inhibited BRCA cell proliferation and migration in BT-549 and HCC1599 cells and reduced tumor growth in vivo by sponging miR-107." (PMID 34827600, 2021). "Recent studies have reported that lncRNA KCNQ1OT1 can affect tumor development and progression via modulation of gene expression in Wnt/β-catenin signaling pathway." (PMID 34704918, 2021). "We checked the expression profile of KCNQ1OT1 and other hub network genes in tumor group and normal group in TCGA data set." (PMID 34630508, 2021). "Previous studies have shown that KCNQ1OT1 is upregulated in colon cancer and is therefore considered to be a tumor marker." (PMID 32953888, 2020). "High expression of KCNQ1OT1 was identified in LUAD SBRT-resistant cells and tissues, positively associated with a large tumor, advanced clinical stage, and a lower response rate to concurrent therapy." (PMID 33082306, 2020).
tumor (continued). "In this study, we described that KCNQ1OT1 is upregulated in IR-resistant LUAD cells and tumor tissues, which is associated with a low objective response rate and poor prognosis in LUAD patients." (PMID 33082306, 2020). "We found that the stable KCNQ1OT1-knockdown group exhibited significantly decreased the xenografted tumor growth and a decreased tumor burden compared to the control group." (PMID 32332718, 2020). "In summary, this study reveals a novel mechanism, the KCNQ1OT1/miR-15a/PD-L1 axis simultaneously promotes multiple tumor-autonomous malignant phenotypes and inhibits the function of CD8+ T cells." (PMID 32821247, 2020). "The lowest tumor risk regards KCNQ1OT1:TSS-DMR hypomethylated subgroup, although there is a remarkable tumor variability." (PMID 33101381, 2020). "The four main molecular subtypes of BWS (KCNQ1OT1:TSS-DMR-LOM, H19/IGF2:IG-DMR -GOM, UPD, and CDKN1C mutations) are characterized by specific genotype-phenotype correlation to tumor development risk." (PMID 33101381, 2020). "In this study, we demonstrated that KCNQ1OT1 was upregulated in OS and promoted tumor growth by contributing to aerobic glycolysis." (PMID 32332718, 2020). "The results revealed that KCNQ1OT1 expression was significantly upregulated in NSCLC tissues compared to adjacent non-tumor tissues." (PMID 32377169, 2020). "The impact of KCNQ1OT1 on MTX‐resistant CRC tumour growth and related proteins in the cAMP signalling pathway was examined with a tumour xenograft assay." (PMID 30997746, 2019). "MiR-145-5p, a target of KCNQ1OT1, was found to be significantly down-regulated and was a tumor suppressor in some tumors." (PMID 31827399, 2019). "KCNQ1OT1 is up‐regulated in MTX‐resistant CRC tumour tissues and acts as the sponge of miR‐760, thus promoting the expression of the target gene PPP1R1B by activating the cAMP signalling pathway." (PMID 30997746, 2019). "qRT‐PCR analysis revealed that lncRNA KCNQ1OT1 was markedly overexpressed in MTX‐resistant CRC tissues compared with its expression in MTX‐sensitive tumour tissues (P < 0.01)." (PMID 30997746, 2019). "Tumor growth in the KCNQ1OT1 knockdown group was substantially suppressed compared with that in the control group." (PMID 29970910, 2018). "Using online database analysis, we predicted that the lncRNA KCNQ1OT1 facilitates tumor growth and chemo-resistance by acting as a competing endogenous RNA (ceRNA) to modulate the expression of miR-211-5p." (PMID 29970910, 2018). "The tumor weights from the KCNQ1OT1 knockdown group were significantly lower than those of the control group." (PMID 29970910, 2018). "KCNQ1OT1 was one of the most upregulated lncRNAs in tumor issues compared to the control (fold change: ~57)." (PMID 27992366, 2017). "MEG3, HOXA13, and KCNQ1OT1 were all overexpressed in HCC tumor tissues (P = 0.001, P < 0.001, and P = 0.004, resp)." (PMID 26136615, 2015). "All such studies concluded that overexpression of KCNQ1OT1 was associated with HCC cell growth and may be potential new therapeutic targets for patients with high intra-tumor transcript levels." (PMID 40699747, 2025). "Interestingly, wo found that XIST, SNHG14, NEAT1, LINC00943, KCNQ1OT1 have pro-tumor functions in various cancers but DHRS4-AS1 can inhibit tumor development." (PMID 40015977, 2025). "Compared with non‐tumour tissues, only KCNQ1OT1 was significantly low m6A methylation in LSCC." (PMID 34850551, 2022). "Real-time PCR analysis showed that after lncRNA KCNQ1OT1 was knocked out, the expression of E-cadherin in nude mouse tumor tissues was significantly increased, whereas the expression of Vimentin in nude mouse tumor tissues was significantly decreased." (PMID 35432529, 2022). "Based on this, this research was conducted to figure out whether tumor-derived EVs delivered c-Myc to manipulate KCNQ1OT1/miR-556-3p/CLIC1 axis to affect GC development." (PMID 35260554, 2022). "The results showed that KCNQ1OT1 was upregulated in tumor tissues and cancer cell-derived exosomes." (PMID 36591473, 2022).
tumor (continued). "MiR-3666/KLF7 axis, as the downstream target of KCNQ1OT1, regulate tumor growth." (PMID 36545680, 2022). "Taken together, knockdown of Kcnq1ot1 suppressed OSCC tumor growth." (PMID 35778739, 2022). "Additionally, HYOU1 overexpression abolished the suppressing effects of silenced KCNQ1OT1 on the malignant behaviors of CC cells and tumor growth." (PMID 34704918, 2021). "On the other hand, it has been reported that KCNQ1OT1 could be used as ceRNA in combination with miR-7-5p/miR-27b-3p/miR-4458 to regulate tumor progression." (PMID 33345272, 2021). "However, more comprehensive studies utilizing a varied population of MSSCC patients are needed to better understand the correlation of KCNQ1OT1 expression with tumor size, differentiation, or prognosis in this patient population." (PMID 34827600, 2021). "In addition, we verified that KCNQ1OT1 was significantly increased in tumor tissues compared with that in adjacent tissues (p < 0.05)." (PMID 34350172, 2021). "Herein, results revealed that KCNQ1OT1 could aggravate the malignant behaviors of CC and facilitate tumor growth through modulating miR-296-5p/HYOU1 axis, consequently developing promising molecular targets for CC therapeutics." (PMID 34704918, 2021). "Among them, the tumor-promoting effect of lncRNA KCNQ1OT1 is through the autocrine effect of tumor cell-derived exosomes, which mediates the miR-30a-5p/USP22 pathway to regulate the ubiquitination of PD-L1 and inhibits CD8+ T-cell response, thereby promoting CRC development." (PMID 34350172, 2021). "Furthermore, KCNQ1OT1 exerted tumor promotion in HCC cells via suppressing miR-29a-3p to regulate CBX3 expression." (PMID 34008749, 2021). "For example, in NSCLC, lncRNA KCNQ1OT1 and AWPPH expressions are significantly up-modulated in tumor tissues, and their high expressions were correlated to adverse prognosis; KCNQ1OT1 and AWPPH can enhance the proliferation, migration and invasion of NSCLC cells, respectively." (PMID 34346845, 2021). "Histological analysis further verified the tumor-promoting effect of KCNQ1OT1/XIST overexpression." (PMID 34521445, 2021). "Furthermore, KCNQ1OT1/XIST aggravated tumor growth in vivo by regulating endoplasmic reticulum stress and cell apoptosis." (PMID 34521445, 2021). "Therefore, we constructed a tumor model of KCNQ1OT1 in wild mice, and the results showed that tumor weight and volume were significantly increased when KCNQOT1 expression was elevated (p < 0.05)." (PMID 34350172, 2021). "In addition, KCNQ1OT1 promoted OC progression and supported in vivo tumor formation via targeting the miR-212-3p/LCN2 (Lipocalin-2) axis." (PMID 34827600, 2021). "LncRNA KCNQ1OT1 is located on chromosome 11p15.5 and plays an essential role in tumor progression." (PMID 33994860, 2021). "To conclude, KCNQ1OT1 could aggravate the malignant behaviors of CC and facilitate tumor growth through modulating miR-296-5p/HYOU1 axis." (PMID 34704918, 2021). "Concomitant reducing both KCNQ1OT1 and miR-15a in PC cells abolished the effects of KCNQ1OT1 silencing alone, suggesting that KCNQ1OT1 was essential for maintaining multiple malignant phenotypes of PC cells, and targeting miR-15a allowed for the pro-tumor activities of KCNQ1OT1." (PMID 32821247, 2020). "The expression of KCNQ1OT1 was upregulated in tumor tissues." (PMID 32953888, 2020). "The findings suggest that up-regulating miR-15a or down-regulating KCNQ1OT1 and PD-L1 may become a promising therapy that not only targets tumor evasion, but also inhibits malignant growth of PC cells." (PMID 32821247, 2020). "Additionally, the higher level of tumor KCNQ1OT1 was observed in stage III and IV patients than that of stage I and II patients." (PMID 33082306, 2020). "The data showed that KCNQ1OT1 expression positively correlated with tumor size and TNM stages." (PMID 32564010, 2020). "Additionally, we found that miR-372-3p was negatively correlated with KCNQ1OT1 expression in LUAD tumor samples." (PMID 33082306, 2020).
tumor (continued). "KCNQ1OT1 levels were at least 4-fold higher in tumor tissues compared to normal colorectal samples." (PMID 32564010, 2020). "Importantly, KCNQ1OT1-depleted tumors were significantly more sensitive to IR, with a dramatic tumor growth delay when compared with KCNQ1OT1 depletion alone or the control with IR." (PMID 33082306, 2020). "Xenograft tumor model was structured to prove the biological role of KCNQ1OT1 of CRC in vivo." (PMID 32760218, 2020). "Furthermore, high KCNQ1OT1 expression was confirmed to correlate with large tumor size and an advanced clinical stage." (PMID 33082306, 2020). "We identified KCNQ1OT1 a tumor facilitator in BC development and it could hopefully become a diagnosis biomarker and therapeutic strategy for BC patients." (PMID 31827399, 2019). "In general, PCBP2 upregulation can rescue tumor-inhibitor role of KCNQ1OT1 depletion in BC." (PMID 31827399, 2019). "MiR-145-5p inhibition and PCBP2 up-regulation could countervail the tumor-inhibitor role of KCNQ1OT1 knockdown in BC." (PMID 31827399, 2019). "Interestingly, the difference in tumor weight and growth between the KCNQ1OT1 knockdown and control groups was much more significant in the group treated with cisplatin than in the group given PBS." (PMID 29970910, 2018). "Additionally, silencing KCNQ1OT1 suppressed tumor growth in a CRC mouse model." (PMID 39123348, 2024). "In addition, lncRNA KCNQ1OT1, which is overexpressed in tumor tissues and tumor cell-derived exosomes, could regulate PD-L1 ubiquitination via the miR-30a-5p/USP22 pathway, thereby promoting CRC immune escape." (PMID 37760852, 2023). "An important aspect of BWS diagnostics is childhood tumor prediction since imprinting aberrations in the imprinting center IC1 (also called the H19/IGF2 Differentially Methylated Region, DMR) are associated with high tumor risk whilst those in IC2 (KCNQ1OT1 DMR) are not." (PMID 35860466, 2022). "In addition, we analyzed the effect of KCNQ1OT1 on tumor vascular markers." (PMID 35432529, 2022). "Similarly, the results of our analysis suggest that the lncRNA, KCNQ1OT1, acts as a competitive endogenous RNA that competitively binds tumor-suppressive miR-378a-3p, resulting in increased expression of RBMS1 within tumors via the KCNQ1OT1/miR-378a-3p/RBMS1 axis." (PMID 35910231, 2022). "As a result, our data illustrated that tumor-derived EVs could augment KCNQ1OT1 expression and reduce miR-556-3p expression by transferring c-Myc to GC cells to upregulate CLIC1 and activate the PI3K/AKT pathway, so as to enhance GC cell proliferating, migrating, and invasive potential." (PMID 35260554, 2022). "Furthermore, knockdown of KCNQ1OT1 combined with overexpression of miR-370 reduced tumor growth." (PMID 34827600, 2021). "The results of our study indicated that the KCNQ1OT1 ceRNA network could be involved in the regulation of the CRC tumor microenvironment, providing a rationale for the further exploitation of KCNQ1OT1 as a possible functional contributor to and therapeutic target for CRC." (PMID 34630508, 2021). "Interestingly, KCNQ1OT1 has also been shown to exert anti-tumor effects." (PMID 34827600, 2021). "In addition, we used CCK-8 assay, wound healing assay, and Transwell assay to test the effect of exosomes on tumor cells and verify whether they play a role through KCNQ1OT1." (PMID 34350172, 2021). "Therefore, we want to explore whether the dysregulation of PD-L1 in cancer cells is involved in KCNQ1OT1-mediated tumor growth." (PMID 34350172, 2021). "Therefore, we speculate that lncRNA KCNQ1OT1 may affect tumor immunity by interacting with CD155 to affect the prognosis of tumor patients." (PMID 33994860, 2021). "Specifically, we will show that KCNQ1OT1 and miR-124 mediate RB cell progression possibly via regulating SP1 expression and silent information regulator 1 (SIRT1)/c-Jun N-terminal kinase (JNK) signaling, which are strongly associated with tumor cell proliferation, apoptosis, and migration." (PMID 33345272, 2021).